RNU6-1092P (RNA, U6 small nuclear 1092, pseudogene)
Gene: Small nuclear RNA gene on chromosome 8 (100,683,488 to 100,683,574, forward strand). Ensembl gene ENSG00000252764.
Homologues: Orthologues: chimpanzee U6 (100% identical), macaque U6 (95% identical), dog U6 (75% identical), rat LOC120099410 (75% identical). Paralogues in human: RNU6-1060P (89% identical), RNU6-1152P (89% identical), RNU6-1287P (89% identical), RNU6-19P (87% identical), RNU6-272P (87% identical), RNU6-45P (87% identical), RNU6-843P (87% identical), RNU6-98P (87% identical), RNU6-1024P (86% identical), RNU6-1047P (86% identical), RNU6-106P (86% identical), RNU6-1094P (86% identical), and 1286 more.